ERBB3 (erb-b2 receptor tyrosine kinase 3)
Diseases named in the same sentence as ERBB3 in open-access papers (continued):
Sharing a sentence is not in itself a finding about the gene and the disease.
tumor (continued). "ERBB3 influences PI3K/AKT/mTOR pathway activation and epithelial−mesenchymal transition (EMT) in CC, contributing to immune evasion and tumor development, and may interact with immune checkpoints to facilitate tumor escape." (PMID 38835778, 2024). "However, the ERBB2-targeting antibodies trastuzumab and pertuzumab block the formation of signaling-competent ERBB3/ERBB2 heterodimers, and this mechanism has been shown to be critical for the anti-tumor effect." (PMID 38806620, 2024). "In summary, the involvement of NRG1 in promoting ERBB3-mediated signaling and the formation of oncogenic heterodimers with ERBB1, ERBB2, and ERBB4 highlights the significance of NRG1 fusions in driving abnormal cell proliferation and tumor progression." (PMID 38957319, 2024). "Interestingly, in human breast cancer cell lines, miR-125a act as a tumor suppressor and is underexpressed, interfering with the expression of ERBB2, ERBB3 and HUR (an RNA binding protein), promoting antiproliferative effects." (PMID 38954129, 2024). "MiR-323a-3p targets ErbB3/EGFR, promotes apoptosis, and inhibits tumor growth in vivo and in vitro." (PMID 35319011, 2022). "It is thus tempting to speculate that an RTK spectrum beyond ERBB3, EGFR, and AXL might be affected by SLC35B2 levels, depending on individual tumor type and treatment context." (PMID 35798875, 2022). "ERBB3 mutations were identified in 1/40 (2.5%) HER2 negative tumours and 1/29 (3.4%) of HER2-positive tumours, while mutations in ERBB4 were identified in 2/40 (5%) HER2-negative tumours and 2/29 (6.9%) HER2-positive tumours." (PMID 33933113, 2021). "Unlike the small intestinal polyps in the ApcMin/+ model, epithelial-specific deletion of Erbb3 in the AOM model did not result in tumor size reduction, although the number of polyps was increased." (PMID 34843459, 2021). "Our germline ERBB3 mutation is novel for NSCLC and has not been reported (either as a somatic or germline mutation) in any other tumour type." (PMID 34274969, 2021). "ERBB3 has mutations in all tumor regions of GB01 and GB03, whereas GB02 has no ERBB3 mutations in any of its regions." (PMID 33922652, 2021). "Tumour tissue from the proband (III.2) showed weak cytoplasmic ErbB3, with absent staining of normal surrounding lung tissue." (PMID 34274969, 2021). "Candidate pathogenic mutations in untranslated regions (UTRs) and BC-relevant genes regions, including oncogenes (i.e., KRAS, ERBB3, PIK3C2G) and tumor suppressor genes (i.e., FANCC, ATR, SMAD2), were found in organoids, and the majority of them were conserved within the tumor–organoid pair." (PMID 33371412, 2020). "Moreover, we observed that stronger ERBB3 expression was correlated with AFP (p=0.023), GGT (p=0.012), tumor size (p=0.011), tumor thrombus (p=0.047), and TNM stage (p=0.007)." (PMID 32206115, 2020). "Some of the genes involved include VEGFA (angiogenesis), WNT1 (proliferation), ERBB3 (proliferation), SMAD4 (tumor suppressor), NDRG2 (radioresistance) and EGFR (invasiveness) all leading to tumor aggressiveness." (PMID 30842790, 2019). "Altogether, the data suggest that in HNSCC, full EGFR activation is dependent on the ErbB3-neuregulin-1 axis, a hierarchy that has not been previously demonstrated in any tumor type." (PMID 29305574, 2018). "By reviewing the list of genes without impact like ERBB3, CASP8, RAF1 and KRAS (FaDu) as well as KEAP1, KRAS, RAF1 and FANCD2 (SAS), one finds tumor drivers ranked among the top 100 mutated genes in HNSCC." (PMID 29719593, 2018). "We confirmed that EGFR protein is only being measured in the tumor, as immunohistochemistry using an EGFR antibody cross-reactive to mouse and human in both untreated and ErbB3-antibody-treated tumors showed that only the HNSCC tumor cells and not the stroma express EGFR." (PMID 29305574, 2018). "This suggested that ErbB3 signaling is particularly important for aspects of tumor growth related to the in vivo tumor microenvironment that are not required for in vitro growth." (PMID 29305574, 2018).
tumor (continued). "However, expression of the other hypoxia-specific genes: ERBB3 and CA9, ANGPTL4 was the highest at later stages of tumor development." (PMID 30412628, 2018). "In some tumor samples, total EGFR was observed to be increased after anti-ErbB3 antibody treatment." (PMID 29305574, 2018). "Serum ERBB3 in the Fifteen Tasmanian devils without neoplasia (devils 1–15 includes CHD,CHDD and CHJD) ranged from <30–663 pg/ml with a median of 32 pg/mL (30–220; interquartile range)." (PMID 28591206, 2017). "In addition, HCaRG secreted form renal epithelial cells inhibited tumor cell proliferation and suppressed the expression of ErbB receptors (EGFR and ErbB3)." (PMID 29050225, 2017). "We show that ErbB3 inhibition by KTN3379 inhibits mainly AKT signaling while cetuximab predominantly attenuates the ERK pathway, providing a mechanistic rationale for the observed enhanced anti-tumor activity of KTN3379 when combined with cetuximab." (PMID 28723928, 2017). "We show here that nectin-like molecule-4/cell adhesion molecule 4, known to serve as a tumour suppressor, interacts with ErbB3 in the absence of HRG and inhibits the HRG-induced dimerization of ErbB3 with ErbB2 and its activation." (PMID 28900130, 2017). "Since NRG1 is expressed in the majority of HNSCC tumors, we asked whether ErbB3 itself is also expressed in HNSCC patient samples and thus, may serve as a tumor target for anticancer therapy." (PMID 28723928, 2017). "However, we observed enhanced anti-tumor activity when both KTN3379 and cetuximab were combined suggesting that ErbB3 and EGFR act independently of each other at the receptor level." (PMID 28723928, 2017). "We demonstrate that cetuximab treatment primarily inhibits the ERK signaling pathway and KTN3379, an anti-ErbB3 monoclonal antibody, inhibits the AKT signaling pathway, and that dual ErbB receptor inhibition results in enhanced anti-tumor activity in HNSCC models." (PMID 28723928, 2017). "We found that ErbB3, HER2 and NRG1 expression are particularly widespread in HNSCC, in agreement with other published studies, and providing a rationale for evaluation of dual ErbB blockage to improve the benefit of cetuximab treatment in this tumor type." (PMID 28723928, 2017). "We found that unlike NRG1, ErbB3 expression in HNSCC is highly prevalent but rarely overexpressed relative to other tumor types, as determined by mRNA analysis." (PMID 28723928, 2017). "In general, our foundlings indicated that the G/T SNP might serve as a tumor promoter and poor prognosis indicator in GC by affecting the binding of miR-204 and miR-211 on the 3′UTR of ErbB3." (PMID 28924391, 2017). "ERBB3 is in a very different genomic context in the tumour (located on chromosome 4 rather than 5) and has experienced a copy number gain." (PMID 28821767, 2017). "We used the nCounter expression assay (NanoString®) to measure the expression of EGFR, erb-B2 receptor tyrosine kinase 2 (ERBB2), ERBB3, ERBB4, and estrogen receptor 1 (ESR1) genes using mRNA extracted from paraffin-embedded tumor tissues from 203 patients diagnosed with TNBC." (PMID 26907936, 2016). "In contrast, nuclear staining was observed with ErbB3 C-ter in 60 of the 169 (35%) PCa samples, but in none of the non-tumour samples." (PMID 27191720, 2016). "In the absence of external perturbations, the growth of ErbB2-dependent tumours occurs with operational AKT-ErbB3-negative feedback, that is, leading to lower ErbB3 levels, as a result of continued stimulation of AKT." (PMID 27255951, 2016). "Tumor samples were assayed for biomarkers [NRG1, ERBB3, and human papillomavirus (HPV) status]." (PMID 27843803, 2016). "Inhibition of ERBB3 signaling via both blockade of SRC and ERBB1 results in tumor cell death." (PMID 26934000, 2016). "More importantly, resistance could be alleviated with therapeutic antibody blocking ErbB-3 activation, which impaired NRG-1β-driven AKT/PKB and ERK activation, clonogenic growth in vitro and tumor growth in xenograft models." (PMID 26160848, 2015).
tumor (continued). "ERBB3 localises to differentiated cell populations within tumours that are non-proliferative and distinct from cancer stem cells." (PMID 26367378, 2015). "We sought to investigate whether the contrasting expression pattern of ERBB3 and EPHB2 was conserved in multiple tumours or if some tumours contained cells which co-expressed both markers." (PMID 26367378, 2015). "Although western blot data from tumor samples suggest that A5/F4 had no impact on total levels of ERBB3 in the xenografts this does not rule out increased internalization of the receptor." (PMID 25386657, 2014). "When administered at a dose and schedule equivalent to that used for preclinical testing of an anti-ERBB3 antibody that has progressed to clinical development, the A5/F4 oligoclonal (20 mg/Kg each, BIW) significantly reduced (p = 0.004) tumor growth rates as compared to vehicle treatment." (PMID 25386657, 2014). "In conclusion, we have identified ERBB3 as a marker of a GNB/GN-like expression profile, and we suggest a 7-gene expression signature as a complement to histopathological assessment of neuroblastic tumours." (PMID 23835063, 2013). "This would be in line with the finding that PI3K is able to block a negative feedback loop in ErbB3-driven tumour cells, resulting in a compensatory activation of the ERK signalling pathway." (PMID 23308242, 2013). "In cell lines, NRG1β expression was significantly inversely related to ERBB3, but this was not confirmed in tumours." (PMID 21364580, 2011). "Despite the expression of ErbB3 on the ErbB2‘−’/ErbB3‘+’ MDA-MB-468 tumour model, 125I-ALM failed to accumulate to levels above that seen in blood (0.29±0.07 vs 0.29±0.03% ID per g; P=0.55)." (PMID 18841159, 2008). "Consistent with the proposed hypothesis that bivalent binding will increase tumour retention, optimal targeting of ALM in vivo requires expression of both ErbB2 and ErbB3 on the tumour cell surface." (PMID 18841159, 2008). "However, we observe a significant attenuation of tyrosine kinase signalling in tumours from the bitransgenic MMTV-myr-Akt1, MMTV-c-ErbB2 animals compared with tumours from the MMTV-c-ErbB2 animals, particularly with regard to ErbB3 and Src." (PMID 18700973, 2008). "HRG stimulation promoted physical and functional erbB2/erbB3 interactions and tumor cell growth, whereas no response to EGF or IGF-1 was observed." (PMID 16168116, 2005). "The majority of tumor cells from 78423 R1 were erbB3 negative, although some cells showed weak erbB2 protein expression." (PMID 16168116, 2005). "In addition, many genes in the combined list are prominent oncogenes or tumour suppressors, like BCL2 or ERBB3." (PMID 16271137, 2005). "In contrast, ErbB-3 mRNA was much higher in the primary tumours (and matched normal kidney) than in RCC cell lines, while ErbB-4 message was markedly reduced in tumours compared to normal." (PMID 15956968, 2005). "This included hypermethylation of negative TMRs associated with tumour suppressor genes, such as TGFBR2 and SMAD3, as well as loss of methylation at negative TMRs for the oncogenes ERBB3 and SND1 and for PTPN13, which is described as having both oncogenic and tumour suppressor roles." (PMID 41036619, 2025). "However, clinical trials with inhibitors blocking ERBB3 had little to no efficacy in the colon and showed a tendency toward promoting tumor progression." (PMID 37712424, 2023). "The occurrence of tumor metastasis, however, did not impact the degree of ERBB3 methylation." (PMID 38144565, 2023). "ERBB3 is known to primarily function as an oncogene for the activation of PI3K/AKT and ERK signaling to promote tumor cell proliferation or differentiation; hence, we believe that the inactivation of these pathways might limit cell proliferation, leading to dysplasia of multiple organs." (PMID 31752936, 2019).
tumor (continued). "Ninety-six hours after transfection of ErbB3 SMARTpool siRNAs, tumor cells from CRC cultures were harvested and again probed for levels of EGFR activation, experiments which showed elevated levels of Trop2 and reduced levels of p-EGFR even when ErbB3 was incompletely suppressed." (PMID 29305574, 2018). "Another key finding identified in this report explains a feature of PI3kinase signaling inhibition that has been observed in several tumor models but not well understood, namely the lack of observed efficacy of ErbB3 inhibition in vitro relative to the profound anti-tumor effect in vivo." (PMID 29305574, 2018). "However, it is not the universal determinant because there are ErbB3-negative tumor cell lines whose radiosensitivity is not enhanced by Hsp90 inhibitors." (PMID 28291803, 2017). "We identify ERBB3 as a potential biomarker of DFT1 and highlight current literature supporting the therapeutic possibilities that can be directed towards ERBB3 overexpressing tumours that may be helpful in the elimination of DFT1 from the wild." (PMID 28591206, 2017). "Characterization of circulating tumor cells in the vasculature demonstrated activation of the Erb-B2 receptor tyrosine kinase 3/neuregulin (ErbB3/NRG1) axis and EMT promoted this hematogenous metastasis, and perturbation of ErbB3 signaling inhibited omental metastasis." (PMID 28587302, 2017). "However, trials were not successful as tumour cells developed compensatory pathways by regulating ErbB3 expression and localization." (PMID 27191720, 2016). "Moreover, we and others showed that even the ErbB3 depletion by siRNA was not enough to elicit an apoptotic response in ErbB2-dependent tumours, although it potently inhibited proliferation of tumour cells." (PMID 27255951, 2016). "Unfortunately, anti-ErbB3 antibodies may not result to be highly efficacious as single agents, because of tumor cells ability to escape from ErbB3 inhibition by activation of EGFR and/or ErbB2." (PMID 26862736, 2016). "In addition to EGFR, the levels of mRNA encoding for the other members of the ErbB family, including ErbB2 and ErbB3, showed a decrease rather than an increase in all resistant tumor cell lines." (PMID 27248176, 2016). "However, co-immunofluorescence analysis showed that ERBB3 and EPHB2 marked specific cell populations that were mutually exclusive within tumours with distinct proliferative potentials, the majority of ERBB3+ve cells being non-proliferative." (PMID 26367378, 2015). "However, a sub-group of EPHB2-/ERBB3+ cancer cells were not positive for MUC2 in these tumours (white arrows)." (PMID 26367378, 2015). "However, when xenografts were allowed to grow to 400 mm3 in size prior to weekly antibody treatment, the potent and specific anti-tumor properties of the ErbB3 antibodies against the tumors lacking Trop2 was revealed." (PMID 25238142, 2014). "Furthermore, also in these cases ErbB3 should not be considered the main driver of tumor growth but rather a co-promoting factor." (PMID 23896512, 2013). "We show that CL4 binds EGFR on tumor cell surface as well as the soluble extracellular domain of the receptor with a Kd of 10 nM, while it does not bind to the other members of the ErbB family, ErbB2, ErbB3 or ErbB4." (PMID 21915281, 2011). "Moreover, there was a significant correlation between IRS-1 Y612 and the proliferation marker Ki-67 in these ER+ tumours, suggesting that the potential interplay between erbB3, IRS-1 and Akt in these tumours may culminate in driving cell proliferation." (PMID 21939528, 2011). "Our studies suggest that tumours that overexpress ErbB2 which activate Akt by means of mutating PI3K, PTEN or Akt (rather than via ErbB2/ErbB3 activation of PI3K) may be resistant to ErbB2-targeted therapies." (PMID 18700973, 2008). "This difference in ErbB3 expression strongly suggests that effective tumour targeting with bs-scFvs may not require overexpression of both target antigens relative to normal tissue." (PMID 18841159, 2008).
tumor (continued). "To test the hypothesis that bispecific targeting will increase tumour-targeting selectivity of antibody-based agents, we took advantage of two previously identified scFv, the anti-ErbB2 ML3.9 scFv and the anti-ErbB3 A5 scFv." (PMID 18841159, 2008). "However, we noted that a high percentage of oestrogen receptor-negative tumours (59%), lymph node-positive tumours (63%) and c-erbB2 (63%) were strongly positive for c-erbB3 protein." (PMID 9823984, 1998). "However, if RAS inhibitors are combined with agents antagonizing the ErbB3 phosphorylation, such as trastuzumab, the outcome of RAS inhibition becomes substantially potentiated and comparable to the cytotoxic effects of RAS inhibitors observed for RAS-driven tumours." (PMID 27255951, 2016). "Importantly, this effect was observed when the antibody was administered immediately after cell engraftment, but also when tumors were already established, thus suggesting that anti-ErbB3 therapy may be useful both to limit CSC-induced initiation and to prevent tumor growth of established tumors." (PMID 26160848, 2015). "We believe that new strategies/agents that aim to reduce erbB3 protein levels, such as the antisense oligonucleotide EZN-3920, the HDAC inhibitor entinostat, and the cooperative “sister” miRNAs may hold special antitumor activity as the tumor cells won’t have opportunities to develop resistance." (PMID 24886126, 2014). "However, we could detect only erbB3-derived, and not erbB2-derived, tyrosine-phosphorylated peptides in the majority of PyMT tumours." (PMID 25200860, 2014). "Indeed, ErbB2 has been identified as an oncogene, and anti-ErbB2 antibody has been used as an anti-tumor drug, although ErbB3 is not identified as an oncogene because it may lack enzyme activity." (PMID 22216327, 2011). "The expression of Ebp1, AR, Cyclin D1, ErbB3 and Ki67 were evaluated by immunohistochemistry using three separate tissue micro-arrays containing normal prostate tissues, non-cancerous tissue adjacent to the primary tumor, hormone-sensitive and hormone-refractory cancerous tissues." (PMID 19025630, 2008). "Surprisingly, ERBB3‐ and ERBB4‐KO cells show a completely different behavior, no changes in proliferation and tumor growth, and even accelerated migration." (PMID 37341059, 2023). "Contrarily, non-responder tumours (HCC07-0409 and HCC29-0909A) showed large areas that are positive for p-ErbB2 or p-ErbB3, which is consistent with previous Western blot analyses." (PMID 34156519, 2021). "Immunohistochemical staining indicated that PDX tumours that did not respond to infigratinib highly and uniformly express EZH2, p-ErbB2, and/or p-ErbB3." (PMID 34156519, 2021). "Similar to lapatinib-stimulation of HER2 levels only in castrated mice bearing 22Rv1 tumours, we saw increased EGFR/HER2 (but not EGFR/ErbB3) heterodimerisation with lapatinib only in CRPC cells in CSS." (PMID 31209328, 2019). "Irrespective of the activation source, phosphorylated ErbB3 strongly couples to the PI3K/AKT pathway by means of six p85-binding sites and elicits a potent anti-apoptotic signal that drives tumor growth and survival." (PMID 28723928, 2017). "While there appeared to be a trend toward elevated NRG1 levels and an increase in tumor shrinkage, neither elevated NRG1 nor reduced ERBB3 expression predicted for response to duligotuzumab or against response to cetuximab." (PMID 27843803, 2016). "This link was less obvious when the primary tumor was negative for the biomarker (5/16 for ERBB1 and 2/5 for ERBB3)." (PMID 26217940, 2015). "In addition, these non-proliferative ERBB3+ cells may still have a role to play during tumour recurrence as it has been reported that post-mitotic intestinal cells can de-differentiate, acquire stem cell like properties and initiate tumourigenesis in some cases." (PMID 26367378, 2015). "One tumour was characterised by the absence of EPHB2+ cells and presence of a large population of double negative cells (EPHB2-/ERBB3-, 85.1% of cancer cells)." (PMID 26367378, 2015).